IL6 (interleukin 6)
Diseases named in the same sentence as IL6 in open-access papers (continued):
Sharing a sentence is not in itself a finding about the gene and the disease.
Sepsis (continued). "miR-25-5p can improve brain injury caused by sepsis by inhibiting the thioredoxin-interacting protein TXNIP/NLRP3 pathway; reducing the levels of TXNIP, NLRP3, and cleaved caspase-1; and inhibiting the expression of inflammatory factors (such as IL-6, IL-1β, and TNF-α and peroxide)." (PMID 37629199, 2023). "Similarly, the elevated cytokine response seen in GAD could contribute to the increase of CRP and IL-6, which are pro-inflammatory cytokines that are known to be significant in sepsis." (PMID 37731448, 2023). "IL-6 levels are higher in patients who died from severe sepsis and among pro-inflammatory cytokines, and plasma IL-6 levels have the best correlation with the mortality rate of sepsis patients, indicating that IL-6 is the key cytokine in the pathophysiology of severe sepsis." (PMID 37372931, 2023). "IL-6 levels correlate well with the severity of sepsis and could be used as a prognostic biomarker." (PMID 35615626, 2022). "Therefore, blocking the IL-6 signaling pathway in MZ B cells at appropriate time points after the onset of sepsis through anti-inflammatory therapy remains a promising treatment for sepsis." (PMID 36425582, 2022). "TNF-α, IL-1β, and IL-6 are the major inflammatory factors that could contribute to sepsis." (PMID 36142743, 2022). "IL-6 and IL-10 levels between Gram bacteria types in severe subgroups (bloodstream infectious patients with higher serum cytokines and sepsis patients with ARDS) might reflect the existence of other inflammatory responses that is independent of the initial bacterial infection." (PMID 36544765, 2022). "ELISAs showed that the protein levels of these two inflammatory cytokines (IL1β and IL6) followed similar expression patterns as the mRNA expression levels Together, these data showed that Rabeprazole treatment accelerates the resolution of sepsis-induced lung inflammation." (PMID 35563731, 2022). "Additionally, LR12 treatment protected mice from sepsis-induced vascular dysfunction, measured by improved vascular contractility, and attenuated IL-6, TNF-α, and IL-10 expression as well as NOS and COX signaling pathway activation in murine aortas and mesenteric arteries." (PMID 35784361, 2022). "These associations between pre-sepsis immune dysfunction and mortality are supported by studies showing that sepsis impairs production of IL-1, IL-6, TNF-α, IL-12, and IFN-γ and suggesting that this sepsis-induced immunosuppressive state may be augmented by release of IL-4 and IL-10." (PMID 35271683, 2022). "As these authors suggest, the increased IL-6 mRNA levels in the diaphragm could be triggered by the overload of this muscle by the increased work of breathing due to metabolic disturbances after liver injury or sepsis." (PMID 35408999, 2022). "These factors then drive systemic inflammation and associated septicemic pathology, with IL-6 in particular being an important driver of this response, while TNF-α additionally regulates immune cells and is produced in large quantities in the context of sepsis." (PMID 35978995, 2022). "Therefore, TNF-α and IL-6 are recognized as proinflammatory cytokines for sepsis." (PMID 36110326, 2022). "Therefore, it was also confirmed that anti-IL-6 receptor monoclonal antibodies can ameliorate the inflammation in burn mice in addition to anti-IL-6 monoclonal antibodies As the studies of IL-6 signal transduction pathways continue, IL-6 had emerged as a potential target for treatment of sepsis." (PMID 36160407, 2022). "In murine models of LPS-induced sepsis and bacterial sepsis, B-1 cell-deficient mice showed exacerbated sepsis severity and increased mortality, accompanied by increased levels of proinflammatory cytokines TNF-α and IL-6 and decreased levels of IL-10 in the plasma, lung, and gut." (PMID 36425582, 2022). "Interestingly, the IL-6−/− mice had developed sepsis prior to 24 hpi." (PMID 35297653, 2022).
Sepsis (continued). "In this study, cytokines TNF, IL-6, IL-10, IFN-γ, IL-27, alarmins Hsp72 and Hsp90, and markers associated with inflammation (CRP, procalcitonin, lactate) and stress (glucose) exhibited early-onset induction, which was strongly correlated with an increased TOS/TAC ratio in sepsis." (PMID 35204114, 2022). "In addition, previous studies suggested that PE treatment could decrease TNF-α and IL-6 levels in the plasma and alleviate myocarditis of sepsis rats." (PMID 36685596, 2022). "Early markers like IL-6 and later markers like CRP are helpful in the diagnosis of neonatal sepsis considering the clinical aspect of the neonate, the gestational age, maternal risk factors and the time (age of the neonate regarding early-onset sepsis) of blood sampling." (PMID 35345614, 2022). "They found that IL-6 and IL-10 levels were both independently associated with mortality, but that the balance of these inflammatory mediators (IL-6/IL-10 interaction) does not seem to impact either early, intermediate or late mortality in ICU patients with sepsis." (PMID 34945111, 2021). "Based on these data and together with the observation that increased IL-6 plasma level are a risk factor for Critical Illness Myopathy (CIM) correlated with peripheral nerve dysfunction, it is feasible that the IL-6/gp130/JAK/STAT pathway plays a role in sepsis-induced muscle atrophy." (PMID 34572540, 2021). "In addition, more than 20 clinical studies are currently registered on ClinicalTrials.gov (accessed on 12 January 2020) that aim to evaluate the efficacy of monoclonal antibodies against IL-6 (e.g., siltuximab, sirukumab, olokizumab, clazakizumab) in Covid-19-induced sepsis and septic shock." (PMID 33803628, 2021). "However, IL-6 concentrations can exceed 1600 pg/mL in patients with sepsis." (PMID 34925324, 2021). "Importantly, NLR combined IL-6 could markedly enhance the prediction power of 28-day mortality of patients with sepsis than the single biomarker." (PMID 33796105, 2021). "The exact pathophysiology of elevated RDW in sepsis is not well understood; however, it is possibly related to a systemic inflammatory response, leading to high levels of pro-inflammatory cytokines (e.g., interleukin-6, tumor necrosis factor-α) and increased oxidative stress in sepsis syndrome." (PMID 34441408, 2021). "Also, cytokine levels (TNF alpha and IL-6) were highest in the CRAB sepsis than CSAB sepsis." (PMID 34493028, 2021). "Interestingly, cytokine network analyses have revealed a network formed by IL‐1β, IL‐6, and IL‐10 during the first day of sepsis, suggesting that these cytokines may take a crucial role in the acute phase of sepsis." (PMID 33719215, 2021). "Considering the possible relationship between inflammation and CLP-induced sepsis, the levels of IL-6, IL-10, and TNF-α in the PLF and blood obtained 8 and 24 h after CLP were measured in order to assess how omentum removal could affect cytokine production in response to infection." (PMID 33815381, 2021). "According to the intestinal mucosal barrier damage in the early stage of sepsis, the early increase in IL-6 (as a proinflammatory factor), FC and D-lactic acid in this experiment can indicate that there may be inflammatory edema of the intestinal wall in the early stage of sepsis." (PMID 35047957, 2021). "In addition, the concentrations of pro‐inflammatory cytokines TNF‐α, IL‐1β, IFN‐γ and IL‐6 in circulation were prominently repressed after wogonin treatment in these two types of sepsis mice, with the levels of these cytokines gradually decreased as the dose of wogonin increased." (PMID 33982381, 2021). "Moreover, sepsis- and MV-elicited ROS may promote the generation of inflammatory cytokines, including IL-6, MIP-2 in rodents, and VEGF." (PMID 33567713, 2021). "Our results showed a close association between TNF-α production but not IL-1β or IL-6 with the NLRP3 29940 G>C variation in sepsis patients, which might be due to the complex inflammatory system in the host." (PMID 34172780, 2021).
Sepsis (continued). "Moreover, the ROC curve illustrated that CRP (AUC [95%CI]: 0.755 [0.636–0.874]), TNF‐α (AUC [95% CI]: 0.660 [0.534–0.786]), IL‐1β (AUC [95% CI]: 0.665 [0.549–0.781]), and IL‐6 (AUC [95% CI]: 0.622 [0.507–0.737]) all had potential in discriminating sepsis deaths from sepsis survivors." (PMID 34761437, 2021). "Reportedly, CGP-60474 could inhibit IL-6 and TNFα to alleviate LPS-induced sepsis in mice." (PMID 34413339, 2021). "In the acute phase of sepsis, macrophages polarize into the M1 phenotype to activate TLRs or other recognition receptors due to impaired intestinal barrier function, bacterial translocation, and increased inflammation, releasing a variety of inflammatory cytokines, such as IL-1β, IL-6, and TNF-α." (PMID 35003009, 2021). "Baicalin could significantly reduce IL-1β in the sera of bacterial infected mice and could inhibit NLRP3 inflammasome activation through augmenting PKA signaling, thereby improving mouse survival in bacterial sepsis and could reduce the level of LPS, TNF-α, and IL-6 in the blood of sepsis mice." (PMID 34938184, 2021). "PJ-34, a PARP-1 inhibitor, may exert its protective effect on intestinal epithelial cells against invasive Salmonella infection by up-regulating IL-6 production, which has anti-inflammatory and cell-protective effects, and counteracts some of the injurious effects of sepsis and endotoxemia." (PMID 34943999, 2021). "Notably, LPS could react with toll like receptor 4 (TLR4), inducing phagocytic cells to generate a variety of proinflammatory cytokines, such as IL-1β, tumor necrosis factor α (TNF-α), and IL-6, which is suggested to be a key pathway in sepsis pathophysiology." (PMID 34055659, 2021). "In addition, our data revealed that silencing circDNMT3B could contribute to the significantly increased level of d‐lactic acid, FD‐40, MDA, DAO, IL‐10 and IL‐6, in comparison to the sepsis group, while the activity of SOD was lower." (PMID 32383354, 2020). "In a mouse model of LPS-induced sepsis in vivo, these authors found that 20 mg/kg of curcumin treatment for 3 days before LPS intraperitoneal injection suppresses the inflammatory response in liver and kidney by inhibiting the cytokines TNFa and IL-6 through targeting miR-155." (PMID 33362557, 2020). "In recent years, studies have suggested that sepsis-induced cardiac dysfunction, the major cause of sepsis mortality (70–90%), is caused by myocardial apoptosis mediated by the MyD88 signal pathway that activates and over-expresses a variety of pro-inflammatory cytokines, including TNF-α and IL-6." (PMID 32423469, 2020). "Additionally, GENT-treated female mice had 4-fold higher IL-6 in lung, whereas (GENT + PTX)-treated male mice presented with higher IL-6 concentrations in lung (~2.5-fold), spleen (2.3-fold), and brain tissues (6-fold) at 5.5 h after sepsis initiation compared to their female counterparts." (PMID 33072121, 2020). "Thus, this study provides evidence that a high TSLP level may lead to organ dysfunction during sepsis, specifically increasing IL-6 and AST levels." (PMID 31480519, 2019). "However, the plasma hepcidin, EPO and IL-6 of sepsis patients upon ICU admission were significantly higher than those of healthy volunteers and decreased gradually throughout the study, but they remained significantly higher on day 7 than those of healthy volunteers (all P < 0.05)." (PMID 31183575, 2019). "Thus, IL-6 appears to be an effective indicator for predicting NS, and could be used as a reference for the early diagnosis of sepsis in neonatal ICUs." (PMID 31671729, 2019). "While the renal excretory defect led to in an increase in serum IL-6 in acute and chronic ischemic AKI models, serum IL-6 in sepsis is predominantly increased from the inflammation-enhanced production and might also directly interfere with liver CYP3A11 production." (PMID 30991873, 2019).
Sepsis (continued). "However, IL-6 can also act as an anti-inflammatory cytokine since it has the ability to induce the release of acute-phase proteins that exert a beneficial effect on sepsis and septic shock." (PMID 30949497, 2019). "Indicating the harmful effect of opioid analgesics in treating critical care patients, murine polymicrobial sepsis with opioid treatment selectively influenced gram-positive gut microbiome translocation and dissemination, inducing its pro-inflammatory effects through IL-6 and IL-17A cytokines." (PMID 31114571, 2019). "However, this upward trend was reversed by MRS/MRM treatment, indicating that methane could reduce the levels of TNF-α and IL-6 to offer a protective effect for tissues and organs during sepsis." (PMID 30779706, 2019). "Interestingly, those with septic shock had both higher pro- and anti-inflammatory levels than patients without shock, with the levels of IL-6 and IL-8 positively associated with IL-10 levels, indicating a correlation with sepsis severity." (PMID 30555806, 2018). "Despite some conflicting studies in mice concerning a direct role of IL-6 in cachexia, the preponderance of evidence shows a strong link between IL-6 and diseases associated with cachexia, including chronic infections, chronic kidney disease (CKD), sepsis, and cancer." (PMID 30081609, 2018). "However this illustrates prognostic rather than diagnostic value and like most cytokines, IL-6 is not specific for sepsis as increased levels are observed in many inflammatory conditions." (PMID 30233566, 2018). "However, it has not yet been validated in patients with sepsis, which is closely associated with IL-6 levels." (PMID 30018224, 2018). "Furthermore, high levels of IL-6 correlate with sepsis mortality." (PMID 30041663, 2018). "In the sepsis model, IL-6 is early induced during infection and a significant correlation between the percentage of splenic MDSC and the levels of circulating IL-6 at the onset of sepsis was observed in both groups of mice suggesting that it might be implicated in MDSC accumulation in the spleen." (PMID 30123776, 2018). "Also, other studies also proved that various miRNAs, such as mi-R210, miR-23b and miR-29a, could inhibit the expression of NF-κB and IL-6 during sepsis via influencing different immune cells." (PMID 29207683, 2017). "Although IL-6 has both anti- and proinflammatory properties and its systemic levels increased after moderate exercise, the response of this specific cytokine to sepsis or regular exercise differed from the increase in TNF-α, which sustained the OTR/down-induced inflammatory status." (PMID 29163473, 2017). "However, whether the increased plasma or tissue levels of IL-6 observed in sepsis and ALI/ARDS, contribute to organ injury, prevent it or merely describe it, remains controversial." (PMID 28424078, 2017). "The pro-inflammatory cytokines selectively measured in our patients (TNF, IL-8, and IL-6) represent some of the key pro-inflammatory mediators involved in what has been referred to as the “cytokine storm”, responsible for the clinical features that characterize sepsis." (PMID 31058274, 2017). "Sepsis in general can result in multiple organ failure and death as a consequence of uncontrolled activation of the innate immune system with high circulating levels of pro-inflammatory cytokines such as interleukin 6 (IL-6), IL-8, IL-1β and tumor necrosis factor α (TNFα)." (PMID 28428949, 2017). "Quite surprisingly, mTPOR-MBP was not able to inhibit the increase in plasma concentrations of TNF-α, IL-6 and IL-10 observed in both models, a well-known phenomenon that participates in the initiation and progression of organ damage during systemic inflammation and sepsis." (PMID 26963510, 2016).
Sepsis (continued). "However the specificity and sensitivity of current biomarkers, including C-reactive protein (CRP), Procalcitonin (PCT), and Interleukin-6 (IL-6) are limited in this setting, and recent studies have suggested the use of new biomarkers for sepsis, including analysis of circulating miRNAs." (PMID 26761003, 2016). "In line, IL-6 levels could be established as a prognostic marker in sepsis-patients." (PMID 26761003, 2016). "Thus, a possible explanation for our findings is that CC homozygous patients had lower circulating levels of IL-6; they therefore presented a lower inflammatory response with lower sepsis severity (reflected by a lower SOFA score) and finally, lower risk of death." (PMID 27834822, 2016). "Indeed, recent evidence suggests that high-dose cholecalciferol (vitamin D3) supplementation in patients with severe sepsis or septic shock increases systemic cathelicidin levels, while modulating immunoregulatory cytokines such as interleukin (IL)-1β and IL-6." (PMID 26380991, 2015). "In addition, the levels of TNF-α and IL-6 have been shown to reach a peak as early as 3 h after the onset of sepsis, and the degree of increase may reflect the severity of sepsis." (PMID 25780398, 2015). "These evidences suggest that IL-6 may be an appealing candidate gene for sepsis." (PMID 25734339, 2015). "Furthermore, persistently high concentrations of IL-6 and/or IL-10, were associated with negative outcome of sepsis in humans." (PMID 26410584, 2015). "Furthermore, this study found that, among a panel of 12 cytokines, IL-6 and TNF-α seem to be the only cytokines with a relevant role in the diagnosis of sepsis and that their association with PCT leads to a posttest probability comparable to that achieved by PCT and MR-proADM combination." (PMID 26635427, 2015). "In the 1990s, sepsis was believed to be associated with an exacerbated release of mainly proinflammatory cytokines, such as tumor necrosis factor (TNF-α), interleukin (IL-1, IL-6, and IL-12), interferon-γ (IFN-γ), and macrophage migration inhibitory factor (MIF)." (PMID 25614712, 2014). "C-reactive protein (CRP), tumor necrosis factor-α (TNF-α) and interleukins are among the first-discovered potential biomarkers for sepsis, among which IL-6 and IL-10 may be good choices as biomarkers while CRP and TNF-α are nonspecific biomarkers for inflammation." (PMID 24977412, 2014). "In addition, we demonstrated that plasma-derived IL-6 levels in Nod1- and Nod2-deficient or WT mice were similar 6, 12 or 24 h after severe sepsis, as well as 6 h after non-severe sepsis induction." (PMID 25084278, 2014). "As expected, serum IL-6 concentrations were similar to the group of systemic inflammatory diseases supporting other studies, where IL-6 has been used not only as a general marker of inflammation, but in particular as a prognostic factor in canine systemic inflammatory response syndrome and sepsis." (PMID 23379382, 2013). "The pathogenesis of sepsis-induced mitochondrial injury is associated with free radical generation and the release of a variety of exacerbating inflammatory mediators (e.g. TNF-α, IL-1β and IL-6) which directly or indirectly influence mitochondrial function and energy production." (PMID 24039949, 2013). "In both univariate and multivariate analyses (including procalcitonin, IL6, C-reactive protein and platelet count) impedance aggregometry using collagen as the activator proved to be the best and an independent predictor for the diagnosis and prognosis of severe sepsis in critical illness." (PMID 23088388, 2012). "We can conclude that sequential measurements of biochemical parameters, such as AST, ALT, PCT and IL-6, during the early postoperative period can be useful for the early diagnosis of sepsis development and its prediction following oesophagectomy, and to differentiate sepsis from postoperative SIRS." (PMID 22742451, 2012).